SRPX2 (sushi repeat containing protein X-linked 2)
Diseases named in the same sentence as SRPX2 in open-access papers (continued):
Sharing a sentence is not in itself a finding about the gene and the disease.
cancer (19 papers, 2010 to 2025). A tumor composed of atypical neoplastic, often pleomorphic cells that invade other tissues. "Apart from cancer-related roles, SRPX2 is implicated in neurological disorders." (PMID 20964819, 2010). "Previous studies have shown that SRPX2 promoted cancer progression via activating FAK/SRC/ERK pathway." (PMID 39333496, 2024). "In terms of studies on the understanding of the SRPX2 gene and its functions in cancer, the mRNA expression from the TCGA and GTEx database (including 29 types of cancer) was analyzed, and SRPX2 was found to abnormally express in multiple tumors." (PMID 35935582, 2022). "The pathogenic role and impact of SRPX2 in GBM is less well characterised, despite been well studied in cancer." (PMID 36412091, 2022). "SRPX2 interacts with the D1 and D2-D3 extracellular domains of uPAR to enhance cancer invasion and metastasis by regulating multiple downstream signaling pathways, including the integrins/FAK pathway, the MAPK pathway, and the PI3K/Akt pathway." (PMID 35935582, 2022). "Previous reports have demonstrated that the CM of SRPX2-producing cancer cells strikingly intensifies the cell proliferation of vascular endothelial cells." (PMID 32455867, 2020). "Cytoplasmic expression of SRPX2 is found in other cancers, and our results are consistent with those reports." (PMID 32455867, 2020). "Our results suggest that SRPX2 promotes vascular and lymphatic endothelial cell migration, the adhesion of HUVECs and HDLMVECs to cancer cells, and the elevation of MVD and LVD in OSCC." (PMID 32455867, 2020). "SRPX2 expression is regulated by miR-149 and miR-192/215, but the mechanism of SRPX2 expression regulation and activation in cancer is not well understood." (PMID 32455867, 2020). "The conditioned-medium of SRPX2-producing cells markedly enhanced cellular adhesion in various cancer cell lines; this result can be explained by the biological function of SRPX2 as a proteoglycan." (PMID 22242148, 2012). "Our findings provide key glycobiological insight into SRPX2 in cancer cells and demonstrate that SRPX2 is a new member of the cancer-related proteoglycan family." (PMID 22242148, 2012). "Vascular endothelial cells HUVEC markedly express SRPX2 to the same extent as high-expressing cancer cell lines." (PMID 22242148, 2012). "In general, SRPX2 was reported as overexpressed in cancer while SRPX and CCDC80 were identified as downregulated in malignant conditions." (PMID 20964819, 2010). "Furthermore, our identification of SRPX2 as a downstream target of circSEC24B sheds light on the molecular mechanisms by which circRNAs regulate cancer progression." (PMID 39333496, 2024). "Meanwhile, the cancer-promoting effect of SRPX2 can be reversed by 3-MA." (PMID 39333496, 2024). "To further confirm whether SRPX2 expression is indeed upregulated in PTC, we performed immunohistochemical (IHC) analysis of SRPX2 expression in cancer and paracancerous tissues." (PMID 37306872, 2023). "The abnormal expression of SRPX2 is a common molecular characteristic of human cancers and enhanced cell metastasis and invasion by regulating the focal adhesion kinase (FAK) signaling pathway, epithelial-mesenchymal transition (EMT), angiogenesis, and glycosylation." (PMID 35935582, 2022). "Researchers have found SRPX2 may yield several clinically relevant insights in patients with cancers." (PMID 35935582, 2022). "Additionally, SRPX2 exerts essential roles in pan-cancers because of participating in stem cell differentiation of human embryonic." (PMID 36385962, 2022). "It has been reported that SRPX2 promotes the progress of malignant in osteosarcoma by activating YAP1, which is closely associated with drug resistance, malignant phenotypes as well as expansion of cancer stem cells." (PMID 36385962, 2022). "Anomalous SRPX2 exerts substantial functions in multiple cancers." (PMID 36385962, 2022).
cancer (continued). "Therefore, EMT process plays an important role for SRPX2 to induce cancer invasion and metastasis by various pathways including the Hippo signaling pathway, PI3K/Akt/mTOR signaling pathway, MAPK signaling pathway, and Wnt/β-catenin signaling pathway." (PMID 35935582, 2022). "Although recent studies have revealed the critical role of SRPX2 in the occurrence and progression of various cancers 11, 12, the functionality of SRPX2 on FMT remains unknown." (PMID 34093874, 2021). "Additionally, the NFATc3/SRPX2 axis participates in human embryonic stem cell differentiation, indicating that SRPX2 plays a critical role in pan-cancers." (PMID 34660598, 2021). "XCL1 (log2(FC) = 1.33, FDR = 8.71e-05) and SRPX2 (log2(FC) = 1.45, FDR = 0.0002) have been reported to enhance cancer progression and promote cancer migration, the up-regulation of which was mainly caused by de-methylation in the stage IV cancer." (PMID 25648588, 2014). "The ability of OTUB1 to deubiquitinate SRPX2 in an acetylation-dependent manner suggests that protein acetylation may play a critical role in modulating the effects of circRNAs and deubiquitinating enzymes on cancer progression." (PMID 39333496, 2024). "Therefore, this review provides compelling evidence that SRPX2 might be a therapeutic target for inflammation and cancer-related inflammation for future cancer therapeutics." (PMID 35935582, 2022). "The 95 % confidence intervals of the hazard ratios of P4HA3, SRPX2, DCN, OMD, and TCF4 all excluded 1 in multivariate analysis in both cancer sets." (PMID 27809802, 2016). "In addition, GFPT2 and SRPX2, which are closely related to CPA4, also promote the progression of various cancers." (PMID 38494845, 2024). "SRPX2 also exhibited excellent antifibrosis effect via TGFβR1/SMAD3/SRPX2/AP1/SMAD7-positive feedback loop, indicating that SRPX2 might be a therapeutic target for inflammation and cancer-related inflammation for future cancer therapeutics." (PMID 35935582, 2022). "SRPX2 expression was markedly up-regulated (20.5 fold, p = 0.00014) in cancer tissues, compared with paired noncancerous mucosa samples, whereas the putative tumor suppressor gene SRPX was down-regulated (0.7 fold, p = 0.029) in cancer." (PMID 22242148, 2012). "In many cancer-related microarray experiments (see Introduction section), P-DUDES genes showed diverse expression changes, although most often SRPX and CCD80 were downregulated whereas SRPX2 was upregulated." (PMID 20964819, 2010). "Further analysis suggested that modulation of angiogenesis-related genes (including ANGPTL4, FN1, HSPG2, SRPX2, KLK5, L1CAM, Prr22, FOXJ1, IL24, and TRIM54) potentially contributes to anlotinib resistance, as anlotinib is a multi-targeted anti-angiogenesis drug for cancer therapy." (PMID 31572680, 2019).
brain disorder (2 papers, 2007 to 2009). A disease affecting the brain or part of the brain. "Other homologues of ETX1, notably SRPX2, have been implicated to have a role in speech and cognition, while mutations in this gene have been associated with brain disorders." (PMID 19862339, 2009). "In this study, we have examined the molecular evolution of the SRPX2 gene that causes brain disorders of the speech areas." (PMID 17942002, 2007).
neurodevelopmental disorder (2 papers, 2017 to 2024). A behavioral and cognitive disorder with onset during the developmental period that involves impaired or aberrant development of intellectual, motor, or social functions. "Among these, only PCDH19 and SRPX2 have been demonstrated to cause neurodevelopmental disorder and/or seizures, while a missense variant in CSTF2 gene has been proposed to cause mild speech delay and learning difficulties in affected males." (PMID 39457436, 2024). "This duplication contains 17 genes, of which only the PCDH19 and SRPX2 genes have been related to neurodevelopmental disorders, while for the CSTF2 gene, this relationship is provisional." (PMID 39457436, 2024). "Our data are therefore consistent with mounting evidence that contributions of SRPX2 to neurodevelopmental disorders are more complex than originally thought." (PMID 28440294, 2017).
infection (1 paper, 2025). The state of being infected such as from the introduction of a foreign agent such as serum, vaccine, antigenic substance or organism. "We subsequently performed tube formation and MPG neurite sprouting experiments with Srpx2 or MT-100 treatment after infection with shSrpx2 lentivirus under HG conditions." (PMID 39741183, 2025).
SRPX2 also shares sentences with these, for which no sentence is quoted: autism (3 papers); Intellectual disability (3); Alzheimer disease (1); Aphasia (1); brain tumors (1); cholangiocarcinoma (1); colon adenocarcinoma (1); Dravet syndrome (1); gastric tumor (1); Hypertension (1); liver cancer (1); lung adenocarcinoma (1); multiple sclerosis (1); neurological diseases (1); Obesity (1); Oral Squamous Cell Carcinoma (1); polymicrogyria (1); rectum adenocarcinoma (1); schizophrenia (1); skin cancer (1); small cell lung carcinoma (1); stomach adenocarcinoma (1); thyroid (1); type 2 diabetes mellitus (1); Whooping cough (1).